EGFR (epidermal growth factor receptor)
Diseases named in the same sentence as EGFR in open-access papers (continued):
Sharing a sentence is not in itself a finding about the gene and the disease.
breast carcinoma (continued). "Hence, we assessed whether GPR119 agonist provides synergistic benefit with EGFR-TKI in human breast cancer." (PMID 30497501, 2018). "Hence, in contrast to the prediction of treatment responses to HER2-targeted mAb therapy in breast cancer, EGFR protein expression analysis or its regulation at the DNA level are not in the focus of treatment prediction of response to EGFR-targeted therapy in CRC patients." (PMID 28199979, 2017). "The association between IGFBP3 with epidermal growth factor receptor (EGFR), another breast cancer-related gene, may contribute to tumorigenesis in a manner similar to the long-range interactions between IGFBP3 and breast carcinoma amplified sequence (BCAS1-4) in MCF7 cells." (PMID 29149895, 2017). "Furthermore, overexpression of miR-338-3p reversed the stimulatory effect of EGFR on breast cancer cell proliferation, and the inhibitory effect of miR-338-3p on breast cancer cell proliferation could be rescued by EYA2 overexpression." (PMID 28703807, 2017). "Similarly, Ohno and colleagues engineered donor cells to express the transmembrane domain of platelet-derived growth factor receptor fused to the GE11 peptide, which efficiently delivered let-7a miRNA to epidermal growth factor receptor- (EGFR-) expressing breast cancer cells." (PMID 29410682, 2017). "Hence, an EGFR-targeted therapy may be a promising approach for overcoming resistance to chemotherapy and radiotherapy in breast cancers." (PMID 29100426, 2017). "However, miR-200b is a small, stable and intrinsic molecule, with low side effects, and can more easily access target molecules; thus our findings contribute to the synthesis of new drugs for efficient EGFR inactivation in breast cancer cells and other LeY-EGFR-positive cancers." (PMID 28692034, 2017). "In addition, downregulation of GAS5 has been associated with chemoresistance in some malignant neoplasms, by affecting the sensitivity to adriamycin in gastric cancer, trastuzumab in breast cancer, mTOR inhibition in prostate cancer, and EGFR tyrosine kinase inhibition in wide-type EGFR NSCLC." (PMID 29029523, 2017). "Finally, by proposing a novel pattern of aberrant pairs, called a V-structure, we identified possible mechanisms of dysregulation in resistant-vs-sensitive conditions that may be crucial for breast cancer metastasis and/or EGFR-TKI resistance." (PMID 28288164, 2017). "However, a ligand-independent mechanism was also demonstrated for AXL activation either by reactive oxygen species, by homodimerization upon AXL overexpression, or by heterodimerization with EGFR (epidermal growth factor receptor) as was shown in a breast cancer model." (PMID 28118606, 2017). "Additionally, EGFR is a biomarker for identification of basal breast cancers." (PMID 28852500, 2017). "In this context, a previous study by our group, focused on HER2 over-expressing breast cancer cells, showed that PC-PLC physically associated with both HER2 and EGFR receptors and its inhibition resulted in a decrease in the overall cellular contents of EGFR, HER2 and HER3 receptors." (PMID 28423060, 2017). "Furthermore, expression of the classical breast cancer oncogenes EGFR (epidermal growth factor receptor) and v‐Myc avian myelocytomatosis viral oncogene neuroblastoma‐derived homolog (MYCN) was also positively correlated with CHD7 expression, with Spearman's r = 0.24 and 0.12, respectively." (PMID 28649742, 2017). "Breast cancer targeting using CAR technology has been well documented with studies reporting the generation of CAR for breast cancer-associated tumour antigens such as carbonic anhydrase IX, ERBB2, mesothelin, EGFR variant III (EGFRvIII), carcinoembryonic antigen (CEA), and Mucin-1 (MUC-1)." (PMID 28885562, 2017). "Furthermore, miR-338-3p overexpression reversed the stimulatory effect of EGFR on breast cancer cell migration and invasion as well as EMT, and the inhibitory effect of miR-338-3p on these phenotypes could be rescued by EYA2 overexpression." (PMID 28703807, 2017).
breast carcinoma (continued). "Interestingly, previous reports from more than a decade ago linked EGFR stimulation with enhanced aerobic glycolysis and lactate production in cancer cells including breast cancer, however the mechanism by which the EGFR enhances glycolysis and lactate secretion was just recently reported." (PMID 28611673, 2017). "Epidermal growth factor (EGF) is a crucial factor in mammary gland development and EGFR-targeted therapy provides some promising effects in patients with triple-negative (estrogen receptor-, progesterone receptor-, and erb-b2 receptor tyrosine kinase 2-negative) breast cancer." (PMID 29212252, 2017). "Furthermore, TFF3 has been shown to activate cSRC in MCF7 breast cancer cells, which could in turn mediate EGFR phosphorylation." (PMID 29088778, 2017). "In 2015, Hellenic Cooperative Oncology Group validation study reported that the combination of high EGFR, high HER2, low HER3 and low HER4 mRNA expression was associated with a trend for shorter OS and significantly worse disease-free survival in high-risk early breast cancer patients." (PMID 28978022, 2017). "Taken together, these data demonstrate that brief treatment with EGFR/erbB-2-targeting agents before the onset of tumors may provide lifelong protection from mammary tumors, through the concurrent inhibition of erbB-2 and ER signaling pathways and consequential reprogramming." (PMID 28061785, 2017). "Furthermore, EGFR with ERBB2 are target genes of Lapatinib - Breast cancer drug." (PMID 26892392, 2016). "It has been previously documented for different breast cancer cell lines that sulforapahane downregulates ER-α, EGFR and HER2 proteins as well as PI3K-Akt-mTOR signaling pathway whose overactivity may contribute to resistance of ER-positive cancers to endocrine therapy." (PMID 26014809, 2016). "Thus, there is a need to identify alternate resistance mechanisms to EGFR TKIs in breast cancer." (PMID 27221039, 2016). "However, it remains unclear whether erbB3- and IGF-1R-initiated signaling pathways possess distinct effects on the sensitivity of lapatinib, a dual tyrosine kinase inhibitor against both EGFR and erbB2, in trastuzumab-resistant breast cancer." (PMID 26621843, 2016). "Furthermore, we found that TLK2 may involve the EGFR/SRC/FAK axis to enhance breast cancer cell invasiveness." (PMID 27694828, 2016). "Furthermore, we provide proof-of-principle data utilizing the breast cancer cell line BT474, confirming their dependency on amplification of the epidermal growth factor receptor HER2 and mutation of phosphatidylinositol-4,5-biphosphate 3-kinase (PIK3CA) when grown as tumor spheroids." (PMID 28060271, 2016). "Importantly, our translational studies further suggest that CD44v6 and EGFR co-expression may represent an important prognostic marker for ER+ breast cancers." (PMID 27379207, 2016). "However, even rare breast cancers harboring these specific EGFR mutations are not sensitive to TKI treatment." (PMID 27221039, 2016). "Since the induction of MDR-1 expression by EGF has been reported in breast cancer cells, and EGFR expression is induced as a consequence of β1 integrin ligation, we hypothesized that FNIII14-mediated inactivation of β1 integrin might impact cellular drug efflux capacity." (PMID 27622612, 2016). "Interestingly, the chemical structure of α,β-unsaturated keto functional group of EA is similar to that of irreversible TKIs; however, the role of EA's combinational function on the irreversible EGFR TKIs in breast cancer remains unknown." (PMID 27487128, 2016). "Thus, inhibition of FAM83A could re-sensitize breast cancers to multiple precision therapies, including EGFR TKIs and trastuzumab." (PMID 27221039, 2016). "Moreover, SH003 also reduces EGFR phosphorylation in MDA-MB-231 breast cancer cells." (PMID 27927199, 2016).
breast carcinoma (continued). "Overall, our research suggested that co-drug Asp-UA possessed potential metastasis chemoprevention abilities via influencing EMT and EGFR-mediated pathways and could be a more promising drug candidate for the prevention and/or treatment of breast cancer metastasis." (PMID 27683033, 2016). "Thirty‐two locally/systemically advanced breast cancers treated with first‐line fulvestrant (250 mg/month) were biopsied at therapy initiation, 6 weeks, 6 months and progression and immunohistochemically‐analyzed for Ki67, ER, EGFR and HER2 expression/signaling activity." (PMID 26178788, 2016). "Interestingly, EGFR inhibitor AG-1478 also blocked the upregulation of TAZ mRNA level, but EGF treatment couldn't induce TAZ expression, implicating a heterodimer of ERBB mediating the function of HRG1 in activating TAZ expression in breast cancer cells." (PMID 26885614, 2016). "Accordingly, overexpression of either EGFR or Her-2 in MCF7 cells results in acquisition of oestrogen-independence due to loss of ERα expression further supporting the fact that growth factor signalling and ERα expression have mutual inhibitory action on breast cancer cells." (PMID 27884978, 2016). "Thus, we asked whether EA could potentiate the antitumor effects of irreversible EGFR TKIs in breast cancer." (PMID 27487128, 2016). "Additionally, Kindlin-2 can stabilize EGFR in breast cancer." (PMID 27713156, 2016). "Among many deregulated miRNAs in HER2-overexpressing breast cancer cells, miR-489 expression may be directly regulated by HER2 signaling since treatment with HER2/EGFR dual inhibitor lapatibnib can significantly reverse miR-489 expression status in HER2-positive breast cancer cells." (PMID 26918448, 2016). "Furthermore, it has been shown that crosstalk between diverse kinases may cause EGFR-TKI resistance, especially ligand-independent AXL activation in breast cancer cells." (PMID 27590506, 2016). "Actually, combining a PI3K inhibitor with a small molecule inhibitor of EGFR/HER2/HER3 signaling was shown to have synergistic growth inhibition in breast cancer cell lines in vitro, suggesting that this is a strategy that might be a possible treatment option to be tested in future clinical trials." (PMID 26824988, 2016). "Furthermore, tumours arising in younger women have significantly lower ERα and PR expression, but higher HER-2 and EGFR expression, and in Basal-like breast cancers and breast tumours in younger women, the level and expression of EGFR is an adverse prognostic factor." (PMID 26498662, 2015). "Moreover, in breast cancer cells, at high doses, apigenin resulted in an arrest of cell growth by inhibiting the activity of several kinases involved in the downstream signaling following EGFR activation." (PMID 25918934, 2015). "Moreover, a recent report has shown that ZD6474 can evaluate the feasibility and efficacy of combined VEGFR2 and EGFR in breast cancer cells, which may be an alternative approach to the ongoing conventional cancer radiotherapy." (PMID 25797270, 2015). "Interestingly, recent studies provided evidences that Anxa2 is involved in EGFR signaling, and blocking AnxA2 function or knockdown of Anxa2 expression inhibits the activation of the EGFR downstream pathway and reduces cell migration in breast cancer cell line MDA-MB-231." (PMID 26307676, 2015). "In addition, at least three other european research groups have published the absence of EGFR activating mutations in their cohorts of breast cancer patients." (PMID 26267891, 2015). "Based on our data, it is tempting to propose that PKCζ might acts as the necessary kinase required for EGFR induced NFκB activation during breast cancer progression and future research in this direction will provide more detailed mechanism of breast cancer growth, invasion, and metastasis." (PMID 26218882, 2015).
breast carcinoma (continued). "In addition, pharmacological inhibition of CaCC activity of ANO1 reduced cell viability in HNSCC, esophageal squamous cell carcinoma (ESCC) and breast cancer cells via inhibition of epidermal growth factor receptor (EGFR) and calmodulin-dependent protein kinase II (CAMKII) signaling." (PMID 26196390, 2015). "Moreover, considering previous reports that EGFR signaling is attenuated by cav-1 overexpression in senescent cells and breast cancer, attenuated EGFR signaling shown in parkin KO mouse brain is speculated to be partially mediated by the accumulation of cav-1." (PMID 26627850, 2015). "Interestingly, in both EGFR and Anxa2 high expression groups, E-cadherin presented a significantly higher rate of low expression (P = 0.0002), which indicates a combined effect of EGFR and Anxa2 on breast cancer EMT." (PMID 26307676, 2015). "Importantly, CH12 in combination with trastuzumab had a synergistic inhibitory effect on EGFRvIII+HER2+ breast cancers in vitro and in vivo via attenuating the phosphorylation of EGFR and HER2 and their downstream signal pathways more effectively and reversing STAT3 feedback activation." (PMID 26474285, 2015). "As EGFR has been identified as a promising target for cancer patients for some time, several potent drugs, (e.g. Gefitinib, Erlotinib, Cetuximab, Lapatinib etc.), all approved for the treatment of cancer patients, have been tested in clinical breast cancer studies with overall disappointing results." (PMID 26267891, 2015). "Our data with other compounds suggested that biguanides combined with EGFR inhibitors have the potential to outperform other targeted drug combinations and could be employed in other breast cancer subtypes, as well as other tumor types, with activated EGFR and PI3K signaling." (PMID 25361177, 2014). "Indeed, a number of sensitive Hsp90 clients have been implicated in the pathogenesis of breast cancer, including steroid hormone receptors (ER and PR), receptor tyrosine kinases (HER2, epidermal growth factor receptor (EGFR)) and intermediates of oncogenic signaling cascades (AKT and RAF1)." (PMID 23686707, 2014). "Indeed, 70-80% of breast carcinomas demonstrate evidence of EGFR over-expression, and this may in part be responsible for the RAS pathway activation observed in breast cancer." (PMID 25621297, 2014). "Importantly, the identified mechanism may reveal a possible strategy for sensitizing breast cancer cells to EGFR-targeted therapies." (PMID 25255930, 2014). "In conclusion, we investigated the pivotal role of PI4KIIα in the regulation of EGFR protein levels, and our functional studies indicate that PI4KIIα represents a promising therapeutic target that could be used in combination with existing EGFR treatments used in breast cancer and NSCLC therapy." (PMID 24801752, 2014). "Our results might suggest that EGFR signalling induces within the tumor microenvironment the release by MSCs of soluble factors that might sustain breast cancer cell growth through different signalling pathways that may also be responsible of resistance to anti-EGFR agents." (PMID 25344915, 2014). "Therefore basal-like breast cancers could potentially benefit from EGFR-targeted therapeutic strategies." (PMID 25400978, 2014). "Therefore, increased EGFR expression in ERα positive breast cancers may be a sole important determinant for prediction of anti-estrogen resistance." (PMID 24758408, 2014). "This negative modulation of ER-mediated functions in breast cancer via EGFR signaling may underlie the mechanism of resistance to hormone therapy observed in tumors with high EGFR expression." (PMID 24629097, 2014). "Thus it is reasonable to suggest that erlotinib and metformin could have therapeutic potential in any breast cancer driven by activated EGFR and PI3K pathways." (PMID 25361177, 2014).
breast carcinoma (continued). "Recent studies in mouse mammary tumors have shown that activation of the Ron related receptor, c-Met, is responsible for increased tumor blood flow as well as serving as a mechanism of resistance to a number of targeted therapies including those directed against EGFR, VEGF and B-Raf." (PMID 24980820, 2014). "However, association of KRAS mutations with resistance to anti-EGFR therapies has not been established in breast cancers." (PMID 23601074, 2013). "Moreover, the absence of ER expression in human breast cancer cell lines including MDA-MB231 is associated with higher levels of functional EGFR protein and mRNA." (PMID 24059654, 2013). "Besides HER2 positivity, breast cancers with increased risk to develop brain metastasis are more likely to be estrogen receptor negative, to express the basal cytokeratin CK5/6 and to overexpress EGFR." (PMID 23344048, 2013). "Toward gaining a more thorough understanding of the consequences of altered EGFR signaling caused by VPS4B dysfunction, we developed an iSDMS method to identify changes in the protein synthesis, degradation rates, and dynamic protein expression, in breast cancer SKBR3_shVPS4B cells." (PMID 23431444, 2013). "The anti-invasive effect of oxidized streptolysin O on MDA-MB231 breast cancer cells is characterized by its ability to activate the autophosphorylation of EGFR selectively on tyrosine residues besides Y845, indicating that, in this case, Y845 may not be involved in the anti-cancer malignancy." (PMID 23702846, 2013). "Therefore a panel composed of IGF-1R, CD44v6, GLUT1, CAXII, FGFR2, and EGFR might be suitable for molecular imaging of male breast cancer." (PMID 23308200, 2013). "Thus, inhibiting autocrine EGFR signaling in breast cancer cells may provide a means for reducing paracrine factor production that facilitates microenvironment support in the bone and mammary gland." (PMID 22276166, 2012). "MMP-1 has been proposed as a biomarker for breast cancer; understanding its role in activation of the TGFα/EGFR signal pathway may lead to the use or development of additional targeted agents to suppress this axis, and result in improved treatments for metastatic breast cancer." (PMID 23217186, 2012). "In a group of 47 metaplastic breast carcinomas which belonged to a subset of basal-like breast cancers, no EGFR tyrosine kinase mutations were identified as well; however, the actual ER, PR and cerbB2 status of these tumours analysed were not explicitly clarified." (PMID 21457545, 2011). "Based on these findings, it will be of great interest to examine whether the reported effect of PKCα on tumour cell behaviour involves its stimulatory effect on ADAM17, HB-EGF-shedding, and subsequent EGFR activation, which are all know drivers in breast cancer progression." (PMID 21386996, 2011). "However, EGFR whole gene amplification is frequently observed in patients with breast cancer." (PMID 22132735, 2011). "However, systematic studies appraising EGFR gene amplification and mutations in the same set of cases among Chinese female patients with breast cancer are absent." (PMID 22132735, 2011). "The remarkably lower incidence of protein expression and gene amplification in our breast cancer cases as compared to that reported in Western studies may reflect a truly low prevalence of EGFR gene abnormalities in the Saudi population which may be ethnically related." (PMID 21702909, 2011). "Versican G3 domain appears to be important in local and systemic invasiveness of human breast cancer; our previous investigation demonstrated that versican G3 domain enhanced breast cancer cell growth, migration and systemic metastasis by up-regulating the EGFR-mediated signaling pathway." (PMID 22096483, 2011).